MSN (moesin)
Diseases named in the same sentence as MSN in open-access papers (continued):
Sharing a sentence is not in itself a finding about the gene and the disease.
lymph node metastasis (4 papers, 2008 to 2021). "Enhanced immunoreactivity of all analysed proteins was found to be associated with the presence of lymph node metastases (ezrin, P = 0.047, moesin, P = 0.038, RhoA, P = 0.024, RhoB, P = 0.004 and Cdc42, P = 0.047)." (PMID 23420497, 2013). "have reported that cytoplasmic expression of moesin shows a strong correlation with lymph node metastasis in OSCC patients." (PMID 34987523, 2021). "This may be strong evidence to understand the mechanism that high moesin expression correlates with lymph node metastasis." (PMID 20429915, 2010). "In addition, although this was not significant, ER− cancers with lymph node metastasis tended to display more frequently a cytoplasmic-only moesin staining, without any membrane localization." (PMID 18493596, 2008).
renal fibrosis (4 papers, 2014 to 2022). A final common manifestation of a wide variety of chronic kidney diseases characterized by glomerulosclerosis and tubulointerstitial fibrosis. "Considering the important profibrotic effects of TGF-β1 in renal tubulointerestital fibrosis, we therefore study the role of moesin in such process so as to provide novel therapeutical targets for renal fibrosis and CKD." (PMID 25406076, 2014). "The results revealed that PAS and Masson’s trichrome staining of renal tissue in AGE-treated Msn−/Y mice were much lighter than that in AGE-treated WT mice, accompanied by improvement of glomerular atrophy, indicating the effect of moesin phosphorylation in AGE-induced renal fibrosis." (PMID 36160865, 2022). "Our results thus suggested moesin might be involved in renal fibrosis by interacting with adhesive molecules in renal tubular cells." (PMID 25406076, 2014). "Our results suggested that moesin might be a novel target for attenuating renal fibrosis and could be served as possible strategy for treatment of CKD." (PMID 25406076, 2014). "In the current study, we demonstrated that TGF-β1 could induce moesin expression in human renal tubular epithelial cells and the expression of moesin in the kidney increased in a rat model of renal fibrosis." (PMID 25406076, 2014). "We find that moesin might be involved in renal fibrosis and its effects could be related to interacting with E-Cadherin." (PMID 25406076, 2014). "In conclusion, our results showed that moesin might be involved during renal fibrosis." (PMID 25406076, 2014). "For example, upregulation of DEPs VIM, IQGAP1, and moesin is closely related to EMT and renal fibrosis, and GSN, another DEP, is related to renal tubule epithelial cell apoptosis." (PMID 27036204, 2016). "To further investigate role of moesin in vivo, we continued our study in rat model of UUO which was a well characterized animal model of renal fibrosis." (PMID 25406076, 2014). "In our study, we demonstrated that moesin, which is a member of ezrin/radixin/moesin (ERM) family, was involved in the process of renal fibrosis." (PMID 25406076, 2014). "Moesin is a member of Ezrin/Radixin/Moesin (ERM) protein family but its role in renal fibrosis is not clear." (PMID 25406076, 2014). "Alpha-actinin-1 and Moesin detected after 1 week of UUO may be used as potential biomarkers of tubular injury, whereas Annexin A1, Clusterin and Vimentin may be the candidate markers of renal fibrosis." (PMID 25791774, 2015). "Though the literature suggests moesin and other ERM proteins could promote epithelial plasticity for morphogenesis and migration, their role in renal fibrosis has not been fully investigated." (PMID 25406076, 2014).
Sepsis (4 papers, 2015 to 2023). Sepsis is defined as life-threatening organ dysfunction caused by a dysregulated host response to infection. "High moesin levels have been observed in the blood of cecal ligation and puncture-induced septic mice, and the administration of anti-moesin antibodies alleviates sepsis-associated mortality." (PMID 38130953, 2023). "Therefore, further perspective studies in multiple centers with a bigger population are necessary to confirm the findings and to investigate the molecular mechanisms underlying the action of MSN during the pathogenic process of sepsis." (PMID 33628853, 2021). "In this study, we tested the hypothesis that MSN might be a potential biomarker for evaluating the severity of endothelium damages during the process of sepsis." (PMID 33628853, 2021). "Increased serum MSN contributes to the sepsis-related endothelium damages by activating the Rock1/MLC and NF-κB signaling and may be a potential biomarker for evaluating the severity of sepsis." (PMID 33628853, 2021). "Given that MSN can interact with a variety of effector molecules through different mechanisms, increasing endothelium permeability, MSN may contribute to the pathogenesis of sepsis and be a potential target for design of therapies for preserving the endothelium integrity." (PMID 33628853, 2021).
autoimmune disease (3 papers, 2018 to 2024). A disorder resulting from loss of function or tissue destruction of an organ or multiple organs, arising from humoral or cellular immune responses of the individual to their own tissue constituents. "Although the CFL1 and MSN each showed one co-occurrence in our analysis, the peer studies demonstrate they are associated with the pathological mechanisms in autoimmune diseases." (PMID 39767148, 2024). "Anti-moesin antibodies have been identified in several autoimmune diseases, including anti-neutrophil cytoplasmic antibody (ANCA) vasculitis, acquired aplastic anemia, polyarteritis nodosa, anti-phospholipid antibody syndrome, and Sjogren’s syndrome." (PMID 33669337, 2021). "The identification of anti-moesin antibodies in a spectrum of autoimmune diseases may suggest cross-reactive antibody binding rather than unique autoantibodies to moesin." (PMID 33669337, 2021).
Autoimmunity (3 papers, 2009 to 2022). The occurrence of an immune reaction against the organism's own cells or tissues. "However, as the dominant factors are immune dysregulation and coupled organ-specific autoimmunity, the identified MSN mutation W217X is proposed as a novel autoimmune phenotype of IMD50." (PMID 36119109, 2022). "Moesin, a member of the FERM (4.1 protein, ezrin, radixin, moesin) domain-containing family of proteins interacting with cytosolic tails of trans-membrane proteins, can activate the IL-2/IL-2R pathway, a system well known to be inefficient in maintaining Treg cells in this model of autoimmunity." (PMID 19379516, 2009).
lupus (3 papers, 2020 to 2024). "The RhoA/ROCK pathway has been implicated in lupus pathology in a prior study that showed that increased phosphorylation of the ezrin, radixin, moesin (ERM) proteins interact with CD44 to promote the adhesion, migration and inflammatory response of T lymphocytes." (PMID 37790522, 2023).
meningioma (3 papers, 2018 to 2024). A generally slow growing tumor attached to the dura mater. "In meningioma, moesin labeled strongly the vessels and to a lesser extent the lumens and microlumens in the secretory variant and NF2 labeled the cytoplasm, more intensely in the secretory variant." (PMID 29983887, 2018). "Overexpression of Moesin, or Merlin rescue using a construct lacking the NTD (Merlin∆NTD), was unable to rescue Wnt signaling in Merlin-deficient meningioma cells." (PMID 39251601, 2024). "Overexpression of Moesin, or Merlin rescue using a construct lacking the NTD (MerlinΔNTD), were unable to rescue Wnt signaling in Merlin deficient meningioma cells." (PMID 36993679, 2023).
Squamous Carcinoma (3 papers, 2010 to 2022). "In squamous carcinoma at stage I (SC(I)) or II (SC(II)), the moesin staining was significantly stronger than that of the NC and CIN samples, which average score was 4.4 ± 1.86 and 6.5 ± 2.63, respectively." (PMID 20429915, 2010).
vasculitis (3 papers, 2021 to 2022). "In ANCA vasculitis, anti-MPO antibodies cross-reactive to moesin in glomerular endothelial cells lead to endothelial cell activation and increased glomerular moesin expression." (PMID 33669337, 2021).
actinopathies (2 papers, 2021). "In conclusion, a number of actinopathies are associated with alterations in the homing of lymphocytes and DCs to LNs (WASP, DOCK2, STK4/MST1) and/or in the egress of antigen-experienced lymphocytes from LNs (DOCK2, MSN, STK4/MST1)." (PMID 34867982, 2021).
adenomyosis (2 papers, 2019 to 2020). The growth of endometrial tissue inside the muscular wall of the uterine corpus. "Moesin, a protein encoded in human by the MSN gene, has been proposed as a biomarker for adenomyosis." (PMID 30388215, 2019). "This was supported by the elevated expression of Moesin (Msn) in the Wnk1d/d uteri, a biomarker for adenomyosis in humans." (PMID 33048843, 2020). "Using proteomic analysis, a higher expression of moesin was noted in adenomyosis versus normal endometrium." (PMID 30388215, 2019). "An association between moesin as a marker for EMT has been already proposed and may contribute to our understanding of the pathophysiology of adenomyosis." (PMID 30388215, 2019).
anaplastic large cell lymphoma (2 papers, 2021 to 2024). Anaplastic large cell lymphoma (ALCL) is a rare and aggressive peripheral T-cell non-Hodgkin lymphoma, belonging to the group of CD30-positive lymphoproliferative disorders, which affects lymph nodes and extranodal sites. "In the case of anaplastic large cell lymphoma, the genes linked to protein crotonylation are moesin (MSN), myosin heavy chain 9 (MYH9), and myosin heavy chain 10 (MYH10)." (PMID 39513918, 2024).
antineutrophil cytoplasmic antibody-associated vasculitis (2 papers, 2021). "Additionally, high expression levels of serum IFN-ɤ and TNF-α were observed in patients with myeloperoxidase-antineutrophil cytoplasmic antibody-associated vasculitis who were positive for anti-moesin auto-Ab." (PMID 34577564, 2021).
astrocytoma (2 papers, 2017 to 2021). "And the moesin protein involved in the genesis and progression of astrocytomas and might be regarded as an independent predictor of poor prognosis." (PMID 29221118, 2017). "Our analysis of mRNA expression levels showed that two genes that promote cell proliferation and invasion, DRG2 and MSN, were under-expressed in IDH1-mutant astrocytoma compared to normal tissue and IDH1-wildtype patients." (PMID 34503108, 2021).
autism (2 papers, 2013 to 2023). Persistent deficits in social interaction and communication and interaction as well as a markedly restricted repertoire of activity and interest as well as repetitive patterns of behavior. "More recently, a novel mechanistic explanation was discovered for autism based on a noncoding RNA at 5p14 which was antisense to the MSN gene on chromosome X." (PMID 23840741, 2013).
Cervical Squamous Cancer (2 papers, 2010 to 2022). "Although the relative mRNA expression level of PD-L1 was low in HCS-2 cell, those of ezrin, radixin, and moesin in HCS-2 cells rank high among human uterine cervical squamous cancer cell lines analyzed." (PMID 35807113, 2022). "Furthermore, in the surgical cervical specimen from the patients with FIGO stage at cervical intra-epithelial neoplasia and I-II cervical squamous cell carcinoma, the expression levels of moesin were found to be significantly correlated with tumor malignancy and metastasis." (PMID 20429915, 2010).
Cirrhosis (2 papers, 2018 to 2019). A chronic disorder of the liver in which liver tissue becomes scarred and is partially replaced by regenerative nodules and fibrotic tissue resulting in loss of liver function. "In BDL-RIO rats with advanced cirrhosis, there was still a trend towards less moesin phosphorylation and myosin expression notable." (PMID 29921982, 2018). "In early cholestatic (BDL) cirrhosis, western blot analysis of vasoactive proteins expression revealed a strong reduction of moesin phosphorylation (p-moesin) and myosin light chain production upon treatment with RIO." (PMID 29921982, 2018). "Thus, selective PDGFRβ drug targeting allows the delivery of compounds to inhibit ROCK-mediated HSC contraction during cirrhosis, as shown by the decreased hepatic p-moesin and p-MLC in Y27pPBHSA-treated rats." (PMID 30783172, 2019).
colon cancer (2 papers, 2020 to 2024). "For example, the poor prognosis of colon cancer patients can be correlated with the increased expression of METTL3 in tumor-filtrating myeloid cells, which is regulated by Kla and Kla of MOESIN might make more T cells become Treg cells and promote development of tumor." (PMID 38317138, 2024).
cyst (2 papers, 2015 to 2024). A sac-like closed membranous structure that may be empty or contain fluid or amorphous material. "Moesin may be involved in the process of cyst formation by regulating pulmonary endothelial cells, thereby influencing the lung function of patients with LAM." (PMID 38267973, 2024). "Importantly, fortifying the link between the apical membrane and actin cortex by overexpression of the ezrin/radixin/moesin ortholog ERM-1, significantly rescued cyst formation and ruptures in the pigv-1(qm34) mutant." (PMID 25807459, 2015).
endometrioid adenocarcinoma (2 papers, 2012 to 2022). An adenocarcinoma characterized by the presence of malignant glandular epithelial cells resembling endometrial cells. "Other studies have also indicated that ezrin and moesin are highly expressed at mRNA and/or protein levels in human endometrioid carcinoma tissues and several human endometrial epithelial cancer cell lines, such as RL-95, AN3CA, Ishikawa, HEC-50, and HEC-1-A." (PMID 35456317, 2022). "Previously, we found an over-expression of MSN and under-expression of CLDN7 at the mRNA level in uterine serous carcinoma in comparison to uterine endometrioid adenocarcinoma." (PMID 22272721, 2012).
endometriosis (2 papers, 2022 to 2025). The growth of functional endometrial tissue in anatomic sites outside the uterine body. "Since endometriosis is associated with high Estrogen concentration, we examinedthe effect of E2 on MSN expression." (PMID 35557941, 2022). "MSN is also significantly upregulated in exosomes and vaginal secretions from endometriosis patients compared to disease-free controls." (PMID 40072086, 2025). "The result indicated that the average protein expression of MSN was 0.3217 ng/ml in the control groups, which was significantly lower than endometriosis group (average was 0.9833) (p = 0.0179)." (PMID 35557941, 2022). "Treatment with E2 (10, 50, 100 nm) induced the expression of estrogen receptor α (ERα), led to the activation of the Gα13-RhoA-ROCK-2-MSN signaling pathway, which resulted in the upregulation of MSN expression in endometriosis." (PMID 35557941, 2022). "The roles of RDX and MSN in endometriosis are even less well understood." (PMID 40072086, 2025). "Therefore, we assessed the expression of moesin in exosomes from the vaginal secretion from endometriosis patients (n = 6) and non-endometriosis patients (n = 10)." (PMID 35557941, 2022).
endothelial dysfunction (2 papers, 2012). In vascular diseases, endothelial dysfunction is a systemic pathological state of the endothelium (the inner lining of blood vessels) and can be broadly defined as an imbalance between vasodilating and vasoconstricting substances produced by (or acting on) the endothelium. "Recent studies also found that RhoA/ROCK-dependent moesin phosphorylation involved in the advanced glycation end products-mediated endothelial dysfunction." (PMID 22694757, 2012). "This RhoA/ROCK -dependent moesin phosphorylation regulates AGE-induced endothelial dysfunction." (PMID 22251897, 2012).
ependymoma (2 papers, 2015 to 2018). A WHO grade II, slow growing tumor of children and young adults, usually located intraventricularly. "The apical PM of normal ependyma and the various ependymoma polarity structures, including microlumens, rosettes, and canals, consistently showed PM localization of moesin, similar to NHERF1." (PMID 25775275, 2015). "To investigate the composition of NHERF1 protein complexes in ependymoma, we screened the intracellular localization of the NHERF1 ligands moesin, NF2, PTEN, PDGFRα, EGFR, YAP1, β-catenin and PHLPP2 that have been functionally involved in primary brain tumors." (PMID 25775275, 2015). "NF2 IHC in normal ependymal lining and ependymomas showed only faint or no labeling of apical PM, respectively, suggesting that NF2, unlike moesin, is not a major ligand of NHERF1 in these polarized structures." (PMID 25775275, 2015). "Moesin but not the related ERM family member merlin, the product of the neurofibromin 2 (NF2) gene, hereafter called NF2, has been shown to colocalize with NHERF1 in the microlumens of ependymoma." (PMID 29983887, 2018).
hepatocellular carcinoma (2 papers, 2014 to 2020). A malignant tumor that arises from hepatocytes. "Given the recent report that HCV infection reduces moesin expression we were interested to study the effect of HCV infection on CD81-dependent hepatoma spread." (PMID 24662676, 2014). "A recent report showing that HCV infection reduces the expression of ERM proteins moesin and radixin provides an explanation for our observation that HCV infection limits CD81-dependent hepatoma spread." (PMID 24662676, 2014). "We simultaneously demonstrated that increased expression of ARHGEF10L stimulates hepatocellular tumorigenesis by activating the RhoA-ROCK1 (Rho-associated coiled-coil kinase-1)-phospho-ERM (phospho-Ezrin/Radixin/Moesin pathway) and EMT (epithelial-mesenchymal transition) in hepatocellular carcinoma." (PMID 32565805, 2020). "However, hepatoma cells expressing N-Moesin-GFP, a dominant negative mutant lacking the C-terminal actin-binding domain, showed a reduced ability to spread in response to CD81 ligation." (PMID 24662676, 2014).
Immunodeficiency 50 (2 papers, 2022). "We present a putative new autoimmune phenotype of Immunodeficiency 50 (MIM300988) characterized by antiphospholipid syndrome, Hashimoto’s thyroiditis, leg ulcers, and juvenile tooth loss, associated with W217X mutation of the MSN gene." (PMID 36119109, 2022).
invasive breast carcinoma (2 papers, 2008 to 2020). A carcinoma that infiltrates the breast parenchyma. "Interestingly, p-Moesin was overexpressed in invasive breast cancer cells." (PMID 33292278, 2020). "In addition, we study the expression and sub-cellular localization of wild type and activated moesin in normal breast tissue, benign breast disorders as well as in ER+ and ER− invasive breast carcinomas, highlighting the relationship with lymph node metastasis." (PMID 18493596, 2008).
liver cancer (2 papers, 2016 to 2020). An epithelial or non-epithelial malignant neoplasm that arises from the liver. "B; 2a, b; 3a, b and 4a, b, positive staining rates of DLC-1, Rho A, ROCK2 and moesin in liver cancer tissue samples were 38.75, 78.75, 75.00 and 86.25 % respectively, which was significantly different from those in normal mucosa (83.75, 43.75, 40.00 and 66.25 %) (P < 0.001)." (PMID 26846339, 2016).
liver fibrosis (2 papers, 2021 to 2025). "Furthermore, the association of moesin in liver fibrosis has also been reported using moesin KO mice." (PMID 33907247, 2021).
lung squamous cell carcinoma (2 papers, 2021 to 2023). "Surprisingly, the results showed that whether in LUAD or lung squamous cell carcinoma (LUSC), moesin promotes the infiltration for a variety of immune cells including CD4+ T cells, CD8+ T cells, and DC cells." (PMID 33838692, 2021).
oral cancer (2 papers, 2018 to 2020). "It has been recently reported that moesin knock-down impacts on MT1-MMP expression levels in oral cancer cells." (PMID 32028690, 2020). "As this was the first study about the joint expression of podoplanin and moesin in oral cancer, further investigations based on in vitro assays are necessary for better evaluation of the participation of these molecules together in the tumor invasion process." (PMID 29310601, 2018).